GRIN1 (glutamate ionotropic receptor NMDA type subunit 1)
Diseases named in the same sentence as GRIN1 in open-access papers (continued):
Sharing a sentence is not in itself a finding about the gene and the disease.
schizophrenia (continued). "In our dataset, we detected AMPA and NMDA receptor subunits associated with schizophrenia (i.e., GRIA1 and GRIN2A) and with a spectrum of DD/ID, ASD and seizures, often in co-morbidity (GRIA3, GRIN1, GRIN2A, and GRIN2B)." (PMID 28713243, 2017). "The GRIN1 (rs11146020) gene is located at 9q34, a locus in the promoter region of the NMDAR subunit that has been linked to schizophrenia." (PMID 26819771, 2016). "The GRIN1 (rs11146020) gene product plays a fundamental role in many brain functions, and its involvement in the pathogenesis of schizophrenia has been widely investigated." (PMID 26819771, 2016). "Only a few studies have focused on GRIN1 rs4880213 and the pathogenesis of schizophrenia or mood disorders." (PMID 26819771, 2016). "According to possible effect of both MTHFR polymorphisms and the G1001C variant of GRIN1 on NMDA receptor activity, we also investigated combination of these polymorphisms as a potential risk factor for developing schizophrenia." (PMID 27843994, 2015). "It is possible that deficits in the fear memory of Grin1Rgsc174/Grin1+ mice represent an aspect of the cognitive impairment of schizophrenia." (PMID 23688147, 2013). "In the present study, we subjected Grin1Rgsc174/Grin1+ mice to a comprehensive battery of behavioral tests to further investigate their abnormal behaviors related to neuropsychiatric disorders, such as schizophrenia, bipolar disorder, and ADHD." (PMID 23688147, 2013). "In this study, we examined developmental changes in spine distribution in multiple mouse models of schizophrenia (Grin1 cKO, Hivep2 KO, and Setd1a cKO) and found that experience-dependent spine formation during adolescence, rather than pruning, was commonly affected." (PMID 41533795, 2026). "Both genetic (Grin1-KD) and pharmacological (MK-801) mouse models show robust schizophrenia-like behaviors, offering valuable tools for testing our hypothesized novel pharmacological strategy." (PMID 39612588, 2024). "Genetic variation in GRIN1 has not been associated with schizophrenia, but rare mutations in GRIN2A, which encodes another subunit of NMDA receptors, increase the risk of developing schizophrenia by almost 20-fold." (PMID 38490084, 2024). "The Grin1 mutant mice, in which Grin1 deletion occurs from postnatal day 7, exhibit schizophrenia-typical behaviors, such as impaired prepulse inhibition of startle reflex, deficits of spatial working memory, and exacerbation of amphetamine-induced striatal dopamine release." (PMID 35459266, 2022). "GRIN1 mutations are linked to schizophrenia, neurodevelopmental delay, epilepsy, and glioma, but no other tumors are linked to them." (PMID 36212450, 2022). "GRIN1, GRIN2A, GRIN2B, GRIN2C, and GRIN2D all encode subunits of the N-methyl-D-aspartate receptor (NMDAR), which has been shown to be involved in the development of schizophrenia." (PMID 34946799, 2021). "Several genes were validated in APA sperm that were associated with autism spectrum disorder (CACNA1H, CNTNAP2, GRIN1, SHANK2, SHANK3, ZNF804A), schizophrenia (TCF3, ZNF804A), and bipolar disorder (COMT, DRD4, GRIN1, MBP, PRKCZ, SHANK2, TRPM2, ZNF804A), and in APA blastocysts (CACNA1H)." (PMID 32610362, 2020). "In our study, we selected two SNPs distributed in GRIN1 and GRIA2 genes and tested their effects on the causality connections and structural characteristics of the frontal-striatum-thalamus pathway in Han Chinese schizophrenia patients." (PMID 32372910, 2020). "Whether the polymorphisms in the subunit genes of GRIN1 and GRIA2 receptors contribute to the risk of schizophrenia is still in question." (PMID 32372910, 2020). "Future efforts will be needed to ascertain the role of GRIN1 in the etiology of schizophrenia." (PMID 30704411, 2019). "In addition several lines of evidence have implicated that the N-methyl D-aspartate 1 (GRIN1; OMIM:138249) plays a fundamental role in many brain functions and its involvement in the pathogenesis of schizophrenia has been widely investigated." (PMID 27843994, 2015).
schizophrenia (continued). "The reduction in GRIN1 and GRIN2A in mice bearing DYS and D3 single heterozygosis is consistent with the glutamate hypothesis for schizophrenia which specifies a role for NMDA receptors in either causing glutamatergic dysfunction or mediating cognitive and behavioral sequelae." (PMID 37240042, 2023). "The GRIN1 gene may be related to the occurrence of schizophrenia." (PMID 30704411, 2019). "In some analyses, GRIN1, GRIN2A and GRIN2B were unchanged, but GRIN2A vs. GRIN2B ratio decreased in the PFC of patients with schizophrenia." (PMID 36833173, 2023). "The study aimed to examine whether four selected single nucleotide variants in GRIN1, GRIN2A and GRIN2B encoding NMDA-R subunits, of which two have not been tested before, are linked with the selected clinical phenotype of cognitive dysfunction in schizophrenia." (PMID 33237434, 2021). "Mice with reduced NMDAR expression (GluN1/Grin1 knockdown, KD) that express 5–10% of the normal NMDAR levels, are viable and display schizophrenia-like abnormalities." (PMID 34899420, 2021). "The aim of the study was to explore whether selected nucleotide variants in GRIN1, GRIN2A, and GRIN2B encoding subunits of the N-methyl-d-aspartate receptor (NMDA-R) receptor occur in a selected group of patients with treatment resistant schizophrenia with cognitive impairment." (PMID 33025395, 2021). "Indeed, group 3 cdDMRs were present in genes such as GRIN1, SYN1, and CAMK2A, and others involved in establishing synapse organization and function, a hallmark of early postnatal brain development, implicating abnormal genetic regulation of neuronal connectivity in schizophrenia development." (PMID 31554518, 2019). "The network also includes some well-studied schizophrenia candidate genes (e.g., BDNF, DRD2, GRIN1 and GAD1)." (PMID 20156358, 2010). "The hypofunction of GRIN1 and GRIA2 subunits from glutamic receptors has been hypothesized as the primary process in the etiology of schizophrenia." (PMID 32372910, 2020). "The hypo-function of GRIN1 and GRIA2 subunits from glutamic receptors has been hypothesized as a primary process in the pathophysiology of schizophrenia." (PMID 32372910, 2020). "While the candidate genes used to construct this network were selected using evidence for disease implication derived from two different approaches, the network includes many additional genes of potential relevance to schizophrenia (e.g., GRIA2, GRIN1, GRIN2B, HOMER1, PICK1, and SNAP25)." (PMID 25484875, 2014). "Although Grin1Rgsc174/Grin1+ mice only partially recapitulate symptoms of patients with ADHD, schizophrenia, and bipolar disorder, they may serve as a unique animal model of a certain subpopulation of patients with these disorders." (PMID 23688147, 2013). "All three sets of module genes include well-studied candidate genes for schizophrenia (e.g., DTNBP1), glutamate receptors (e.g., GRIN1), several genes located in the MHC region (e.g., HIST1H1A, HIST1H1C, HIST1H2AB, HIST1H2BB, HLA-E), and genes from the 14-3-3 protein family (e.g., YWHAQ, YWHAZ)." (PMID 23134571, 2012). "Among these 16 SZGenes, several (DRD2, GRIN1, GRM7 and GAD1) are related to three neurochemical hypotheses in the molecular mechanisms of schizophrenia, i.e., the dopamine, glutamatergic and GABAergic hypotheses." (PMID 20156358, 2010). "Grin1 is the main essential subunit of the NMDA receptor, and its downregulation across SCHEMA mutants is consistent with the NMDA hypofunction hypothesis of schizophrenia." (PMID 41022686, 2025). "In contrast to GRIN1, no SNVs in GRIN2A gene have been reported, in OMIM, in associations with schizophrenia and particularly with a clinical phenotype of cognitive deficit in schizophrenia." (PMID 33237434, 2021).
schizophrenia (continued). "Our conclusion is that selected single-nucleotide variants in GRIN1, GRIN2A, and GRIN2B genes of NMDA-R do not seem to be associated with both resistance to schizophrenia treatment with clozapine, and also with the occurrence of cognitive disturbances in schizophrenia." (PMID 33025395, 2021). "Therefore, in this work, we decided to look for another not studied yet variant in the sequence of GRIN1, rs11146020/NG_011507.1:g.4476G > C/5′UTR in association with the selected clinical phenotype of cognitive deficit in schizophrenia." (PMID 33237434, 2021). "Moreover, exome-sequencing studies revealed that rare damaging mutations in GRIN1, GRIN2A, and GRIN2B, which are expected to cause NMDAR hypofunction directly, are found in samples from schizophrenia patients, but not controls." (PMID 31824347, 2019). "Grin1 hypomorphic mice, which express 5–10% of Grin1 compared to wild-type, show increased locomotor activity and stereotypy, impaired social and sexual behaviors, deficits in nest building, and decreased PPI, all of which are considered to be behavioral abnormalities relevant to schizophrenia." (PMID 23688147, 2013). "We selected two loci of rs11146020 and rs3813296 distributed in GRIN1 and GRIA2 genes and tested their main and interaction effects on causality connections and structural characteristics in the frontal-striatum-thalamus pathway in 55 Han Chinese first-episode negative schizophrenia patients." (PMID 32372910, 2020). "A decrease in GRIN1 and GRIN2C mRNA were observed, but no changes in GRN2A and GRIN2B were detected in the PFC of schizophrenia subjects." (PMID 36833173, 2023).
encephalitis (61 papers, 2015 to 2026). An acute inflammatory process affecting the brain parenchyma. "Anti-N-methyl-D-aspartate receptor (NMDAR) encephalitis, the most common type of autoimmune encephalitis, is caused by antibodies targeting the glutamate ionotropic receptor NMDA type subunit 1 (GluN1) of the NMDAR." (PMID 41394831, 2025).
epilepsy (56 papers, 2015 to 2026). A brain disorder characterized by episodes of abnormally increased neuronal discharge resulting in transient episodes of sensory or motor neurological dysfunction, or psychic dysfunction. "Our work reveals an unexpected mechanism for epilepsy caused by a loss-of-function GRIN1 variant and highlights dietary magnesium supplementation as an effective treatment." (PMID 41602908, 2025). "GRIN1 mutations, and more broadly defects in the functionality of these glutamatergic neurons, are typically associated with cognitive impairments, epilepsy, microcephaly, muscular tone abnormalities, and behavior issues." (PMID 39621753, 2024). "The GRIN1 gene, in turn, is associated with cases of epilepsy accompanied by developmental delay, along with hyperkinetic movement disorders and infantile hypotonia." (PMID 38248286, 2024). "It was also reported a personalized therapy in a GRIN1 mutated girl with intellectual disability and epilepsy." (PMID 36006933, 2022). "Phenotypes associated with de novo GRIN1 pathogenic variants include severe early onset psychomotor delay in all reported patients and epilepsies in up to 70% of these patients." (PMID 34413877, 2021). "Variants of GRIN1, which encodes GluN1, are associated with developmental delay, epilepsy, and cortical malformation." (PMID 33062288, 2020). "Mutations of GRIN1 have been reported in patients with neurodevelopmental disorders including early onset epilepsy, severe intellectual disability, motor dysfunction, and generalized cerebral atrophy." (PMID 29163060, 2017). "Hence, AEDs exerted a therapeutic effect on vasogenic epilepsy derived from endothelial CDK5 loss, which results in downregulating epilepsy‐related Phka1 and Btaf1 and upregulating synaptic function‐related Grin1 and Magt1." (PMID 35770064, 2022). "Using a mouse model (Grin1 Y647S+/− mice) that replicates patient phenotypes of epilepsy and cognitive deficits, we examine prefrontal neurotransmission and NMDAR signaling to decipher and treat underlying disease mechanisms." (PMID 41602908, 2025). "Mutations in GRIN1 (encodes the GluN1 subunit), GRIN2B (encodes the GluN2B), and GRIN2D (Glu N2D) present with severe clinical phenotypes, including severe epilepsy with mental retardation and developmental delay." (PMID 36979762, 2023). "Natural variants to the GRIN1 gene, which encodes the obligatory GluN1 subunit of the NMDA receptor, are associated with severe neurological disorders that include epilepsy, intellectual disability, and developmental delay." (PMID 37734923, 2023). "Using genome‐wide RNA sequencing and intergenic interaction analysis of STRING, we found that in addition to epilepsy‐related genes, there are changes in synaptic organization pathway node genes, such as Bdnf and Grin1." (PMID 35770064, 2022). "Epilepsy-associated variants in NMDAR subunits, including GRIN1 gene encoding GluN1 subunits and GRIN2(A-D) gene encoding GluN2(A-D) subunits, respectively, have been reviewed in detail." (PMID 35680847, 2022). "70%–80% of epilepsy is attributed to genetic factors, the GRIN1 gene encodes the NMDA receptor GluN1 subunit, and the NMDA receptor has an important role in epilepsy." (PMID 34035826, 2021). "GRIN1 and GRIN2D code for subunits in the NMDA (N-methyl-D-aspartate) receptors and pathological variants are associated with a severe neurological phenotype including epilepsy." (PMID 40290421, 2025). "Developmental regression, autism, and epilepsy can also be seen in disorders of ion channels (i.e., Dravet syndrome), impairments of receptor expression (i.e., GRIN1), transcription factors (i.e., MEF2C), axonal guidance (i.e., NTNG1), and ubiquination (i.e., RHOBTB2)." (PMID 37511662, 2023). "Moreover, to clarify the effects of AEDs on the mRNA levels of epilepsy‐related and synapse‐related proteins in Cdh5‐CreERT2;CDK5f/f mice, the mRNA levels of Btaf1, Phka1, Nav1, Bdnf, Magt1, and Grin1 were confirmed by qRT‐PCR." (PMID 35770064, 2022).
epilepsy (continued). "After searching in DrugBank, we retrieved a total of 47 anti-epileptic drugs and 151 targets, of which identified 17 target genes (CACNA1A, CHRNA4,CHRNA7,GABRA1,GABRA2,GABRB2,GABRG2,GRIK1,GRIN1,GRIN2B,KCNQ2,KCNQ3,SCN1A,SCN2A, SCN3A,SCN8A and SCN9A) were overlapped with risk genes of epilepsy." (PMID 36006933, 2022). "Related studies have shown that GRIN1, GRIN2A, and GRIN2B mutations can lead to epilepsy." (PMID 35069111, 2021). "Consistent with the converged network module of the PPI subnetworks for autism, epilepsy, and learning/memory, the shared module of these three gene-pathway bipartite subnetworks also involve NMDARs (Grin1, Grin2a, and Grin2b) as hubs connecting to 16 pathways." (PMID 32033586, 2020). "We speculated that the upregulated genes Grin1 and Prkce, Actin2, Mapk1, Psen1, and Nsf might contribute to the comorbidity of autism with epilepsy and abnormal learning and memory." (PMID 32033586, 2020). "We then tested whether either SCZ-linked or epilepsy and DD/ID-linked variants would exert a dominant-negative effect on NMDAR function when co-expressed with an equal amount of wild-type GRIN2A (as well as the obligate GRIN1 subunit)." (PMID 38307912, 2024). "Genetic mutations in the NMDA receptors, such as GRIN1, GRIN2B, and GRIN2D, and mutations in the AMPA receptors, which increase AMPA expression, are suspected of contributing to physiological imbalances in epilepsy, remodeling and reconfiguring the neural networks." (PMID 38248286, 2024). "Variations in GRIN1 are associated with NMDAR functional loss or gain that leads to impaired CNS function and results in neurodevelopmental disorders, including developmental delay, epilepsy, muscle tone abnormalities, microcephaly, and cortical malformation 2–4." (PMID 33062288, 2020). "Accordingly, changes of synapse‐related gene (Phka1, Btaf1, Magt1, and Grin1) and aberrant alternation of NMDA receptors, PSD95, phosphorylation of CaMKII were found in the hippocampus of spontaneous epilepsy mice." (PMID 35770064, 2022). "Genes encoding NMDAR subunits (such as GRIN1, GRIN2A, and GRIN2B) have been identified to be associated with broad-spectrum phenotypes, including epilepsies, epilepsies with NDD, and NDD without seizures." (PMID 38249294, 2023). "In summary, our study suggests that the novel de novo GRIN1 variant (Pro532His) decreases NMDAR function and is associated with profound psychomotor impairment and striking stimulus-induced myoclonus without epilepsy." (PMID 34413877, 2021). "The dysregulated Dnm1, Actb, and Prnp interact with Grin1, suggesting that NMDAR system (NMDARs and their regulators) might contribute to the anti-epilepsy phenotype of this mouse model." (PMID 32033586, 2020). "Interestingly, in both the autism, the EP and LM subnetworks, Grin1 had the biggest betweenness values among DEGs, suggesting that NMDAR might play a key role in regulating molecular pathways underlying autism, anti-epilepsy, and enhanced learning/memory phenotypes." (PMID 32033586, 2020).
Cognitive impairment (35 papers, 2011 to 2025). Abnormal cognition is characterized by deficits in thinking, reasoning, or remembering. "Notably, the synergistic behavioral effects between haloperidol and UNC9994 were consistently detected under NMDAR hypofunction conditions, rescuing hyperactivity and cognitive impairments in Grin1-KD mice and MK-801-treated animals, suggesting NMDAR-dependent underlying biochemical mechanisms." (PMID 39612588, 2024). "The reduction in Grin1, a glutamatergic NMDA receptor subunit, also indicates disrupted excitatory neurotransmission, contributing to cognitive deficits." (PMID 41303666, 2025). "The Grin1KD model is characterised by a 90% reduction in Grin1 mRNA, GluN1 protein, and NMDAR function, which in turn elicits cognitive deficits, reduced social motivation, impaired sensorimotor gating and seizures." (PMID 39749357, 2024).